SCN8A (sodium voltage-gated channel alpha subunit 8)
Diseases named in the same sentence as SCN8A in open-access papers (continued):
Sharing a sentence is not in itself a finding about the gene and the disease.
epilepsy (continued). "Variants detected in epilepsy-related genes (DEPDC5, CHD2, SCN8A and IQSEC2) have been reported in patients with SCN1A variants and were considered to contribute to blended phenotypes comprising features of the disorder associated with the epilepsy gene and Dravet syndrome." (PMID 38891831, 2024). "Moreover, anecdotal evidence and case reports have indicated potential improvements in patients with other sodium channel-related disorders, such as SCN8A-related epilepsy." (PMID 39165469, 2024). "We also examined fenfluramine based on recent clinical evidence suggesting that it might be efficacious in SCN8A-derived epilepsy." (PMID 38895634, 2024). "While it is beneficial to develop novel drugs for SCN8A-derived epilepsy, there is also value in testing FDA-approved compounds, such as CVD, as repurposing drugs could provide faster clinical application." (PMID 38895634, 2024). "Na + channel blockers in the treatment of SCN8A epilepsy may correlate with the effect of such agents on pathological Na + current observed in heterologous systems." (PMID 37880579, 2023). "Similarly, various forms of epilepsy, such as temporal lobe epilepsy, SCN8A epileptic encephalopathy, and Dravet syndrome, are associated with an imbalanced E-I ratio arising from dysfunction in SST and PV interneurons." (PMID 37545878, 2023). "This showed that LEV was ineffective in SCN8A-related epilepsy or that it may have even worsened epilepsy, while VPA exhibited some efficacy consistent with previous studies." (PMID 38174099, 2023). "Our results implicate KCNT1 as a therapeutic target for treatment of SCN1A and SCN8A epilepsy." (PMID 37901435, 2023). "In a study exploring the efficacy of anti-sense oligonucleotide (ASO) therapy for the treatment of epilepsy, a reduction in Scn8a brain expression levels by ASO was found to extend the lifespan and delay SUDEP onset in Kcna1 KO mice; however, seizure burden was not significantly improved." (PMID 37240170, 2023). "Outside of the arrhythmogenic mutations in NaV1.5CTD, recent findings directly link mutations in NaV1.6CTD with early infantile epilepsy [NM_001330260.2(SCN8A):c.5710C>T; p.Arg1904Cys], while early reports of NaV1.6 gain-of-function mutations have described effects on cardiac electrophysiology." (PMID 36821382, 2023). "In contrast to GoF SCN8A mutations causing epilepsy, there are also LoF variants leading to cognitive disorders or autism without epilepsy." (PMID 38003469, 2023). "SCN8A-RES patients may require doses that are higher than those prescribed for most epilepsy patients and, as a result, can be more prone to drug-related adverse events." (PMID 35234610, 2022). "The first SCN8A mutation in a patient with epilepsy was identified in 2012, and as such, treatments for patients with SCN8A mutations are not yet as well-defined as for other sodium channelopathies like DS." (PMID 35153788, 2022). "•Epilepsy surgery reduced seizure burden in patient with SCN8A-related epilepsy." (PMID 35492509, 2022). "In DEEs with a genetic etiology, the underlying pathology contributes—at least in part—to comorbidities independent of seizure burden, as demonstrated in patients with SCN8A‐associated disease who are cognitively impaired but do not develop epilepsy." (PMID 35802036, 2022). "For this reason, we wondered whether NBI-921352 might have broader application in epilepsy beyond SCN8A-RES and in other syndromes of neural hyperexcitability." (PMID 35234610, 2022). "After searching in DrugBank, we retrieved a total of 47 anti-epileptic drugs and 151 targets, of which identified 17 target genes (CACNA1A, CHRNA4,CHRNA7,GABRA1,GABRA2,GABRB2,GABRG2,GRIK1,GRIN1,GRIN2B,KCNQ2,KCNQ3,SCN1A,SCN2A, SCN3A,SCN8A and SCN9A) were overlapped with risk genes of epilepsy." (PMID 36006933, 2022). "Recent works in genomics have identified SCN8A as an epilepsy gene." (PMID 33841294, 2021).
epilepsy (continued). "Several large exome sequencing projects have equally identified 11 de novo mutations of SCN8A in singleton patients with epilepsy with or without intellectual disability." (PMID 33841294, 2021). "Its role in SCN8A-related epilepsy is still unclear; however, it may change RNA stability, modulate transcriptional factors and promoters, modify the initiation of translation, or work as an enhancer or silencer in the splicing pattern." (PMID 33013363, 2020). "Surprisingly, most SCN8A-related epilepsies respond favorably to channel blockers." (PMID 33013363, 2020). "SCN8A-related epilepsies identified in clinical patients through WES and/or NGS." (PMID 33013363, 2020). "Though GS967 has been shown to be an efficacious antiepileptic in rodent models of SCN1A, SCN2A, and SCN8A epilepsies, the safety, tolerability, and antiepileptic efficacy of GS967/Prax330 in human patients with refractory epilepsy remains to be fully investigated." (PMID 32244818, 2020). "Variants in epilepsy‐associated VGSC genes expressed in the central nervous system have also been associated with SUDEP: SCN1A, SCN2A, and SCN8A." (PMID 32449611, 2020). "Mice deficient for Celf4 exhibit a complex seizure disorder that includes both convulsive and non-convulsive seizures resulting from an increased neuronal excitation due to aberrant Nav1.6 (Scn8a) sodium channel activity." (PMID 31293497, 2019). "With the increasing numbers of drug-resistant epilepsies resulting from SCN2A and SCN8A mutations being reported, there is increasing opportunity to gather the necessary data to investigate the potential link between neurotransmitters and voltage-gated sodium channelopathies." (PMID 29184379, 2017). "It is necessary to analyze SCN8A mutations in patients with early onset epilepsy with or without developmental delay or intellectual disability." (PMID 28923014, 2017). "Therefore, we performed qRT-PCR for Scn1a and Scn8a, coding for the voltage-gated sodium channels Nav1.1 and 1.6, as well as for the epilepsy gene Scn2a, coding for Nav1.2, in brain lysates from weaned and 5-month-old mice." (PMID 29046322, 2017). "Co-injecting lentiviruses carrying CDYL-shRNA-GFP and SCN8A-shRNA-mCherry reversed the behavioral alteration in seizure susceptibility induced by knock-down of CDYL, suggesting that CDYL regulates epilepsy susceptibility mainly through Nav1.6 sodium channels." (PMID 28842554, 2017). "While SCN8A null heterozygotes exhibited less seizure susceptibility when compared to wild-type littermates, injecting lentiviruses carrying CDYL-shRNA to SCN8A null heterozygotes abolished the changes of epilepsy susceptibility in these mice." (PMID 28842554, 2017). "We hypothesized that sodium channel blockers could have a beneficial effect in patients with SCN8A-related epilepsy by blocking the overactive Nav1.6 and thereby counteracting the effect of the mutation." (PMID 26252990, 2016). "Large-scale sequencing of patient exomes has revealed the role of SCN8A in human epilepsy." (PMID 26029160, 2015). "Mutations in SCN8A, particularly gain-of-function variants, cause SCN8A developmental and epileptic encephalopathy (DEE), a severe epilepsy syndrome characterized by seizures, cognitive dysfunction, movement disorders, and sudden unexpected death in epilepsy (SUDEP)." (PMID 41623181, 2026). "We selected amitriptyline (AMI), carvedilol (CVD), and nilvadipine for testing in the Scn8aR1620L/+ (RL/+) mouse line based on a previous in vitro screen that suggested these drugs might be efficacious in SCN8A-derived epilepsy due to their ability to inhibit sodium influx." (PMID 38895634, 2024). "It is not clear why a few SCN8A GOF variants caused ataxia as an accompanying symptom of epilepsy." (PMID 38251463, 2023).
epilepsy (continued). "Whether this tonic phase apnea occurs in instances of clinical SUDEP is unclear; however, some epilepsies that commonly present with frequent tonic seizures (e.g., tuberous sclerosis complex, Lennox-Gastaut syndrome, and SCN8A EE) do also experience higher mortality rates, often from SUDEP." (PMID 36160949, 2022). "Our results suggest that NP might be further explored to treat epilepsies which are sensitive to inhibition of voltage-gated sodium channels, including LGS where GOF mutations have been identified in SCN2A (NaV1.2) and SCN8A (NaV1.6) (Epi4K." (PMID 35689251, 2022). "In addition, a growing number of genes initially linked to other neurological phenotypes, such as developmental delay, epilepsy, or ataxia, are now recognized to cause prominent dystonia, occasionally in an isolated fashion (e.g., GNAO1, GNB1, SCN8A, RHOBTB2, and COQ8A)." (PMID 36705216, 2022). "This fits with gain-of-function of SCN8A previously reported in patients with ASD and early infantile epileptic encephalopathies, and six SCN8A variants with disrupted channel inactivation were also identified from 277 patients with ASD, epilepsy, intellectual disability and neuromuscular disorders." (PMID 34525970, 2021). "Indeed, a recent study has also demonstrated that reducing the SCN8A transcript by 25–50% can delay seizure onset in SCN8A models of epilepsy, indicating that a general reduction in Nav1.6 activity may reduce seizure susceptibility." (PMID 34202119, 2021). "Notably, we did not identify variants within SCN2A and SCN8A genes, two genes previously associated with epilepsy and SUDEP." (PMID 32449611, 2020). "No missense variants were identified in exon 5 A of SCN8A in any of the other epilepsy cohorts we evaluated, including 280 individuals with epileptic encephalopathy, 640 individuals with genetic generalized epilepsy, and 1,187 individuals with nonlesional focal epilepsy." (PMID 29121005, 2018). "Part of patients with SCN8A mutations presented only mental retardation without epilepsy." (PMID 28923014, 2017). "Increases in genetic testing have prompted numerous reports identifying four VGSC genes of significant clinical importance in epilepsy: SCN1A, SCN2A, SCN3A, and SCN8A." (PMID 41007641, 2025). "While some biomarkers exist in the broader field of epilepsy, such as EEG-based markers and neurofilament light chain, there are substantial gaps in biomarker availability for SCN8A-RD." (PMID 40830973, 2025). "Notably, variants in the SCN1A, SCN8A, and SCN9A genes, which encode sodium channel proteins, were found with high frequency in both groups, suggesting that disturbances in sodium channel function may play a significant role in the pathophysiology of epilepsy." (PMID 40565516, 2025). "Abnormalities were most frequent in the SCN2A (70.6%) group, followed by the SCN8A (42.9%) and SCN1A (31.6%) groups; one patient with SCN3A-related epilepsy also exhibited abnormal findings." (PMID 41573391, 2025). "Variability in seizure phenotypes among SCN1A-mutated patients suggests potential interactions with other ion channel genes, such as SCN2A and SCN8A, underscoring the polygenic complexity of SCN1A-related epilepsies." (PMID 39906551, 2024). "In 8 patients, one or more epilepsy genes, GRIN2A, TET3, SCN1A, SCN8A, ADGRV1, DLG4, and SLC12A5, were found, and 12 patients had no genetic mutations." (PMID 38813507, 2023). "Successful use of ASOs for severe epilepsies has been reported in preclinical models of SCN1A, SCN2A, and SCN8A encephalopathy." (PMID 36173683, 2022). "We find current evidence for this preferential enrichment among six epilepsy genes: CDKL5 (P = 1.1 × 10−12), KCNQ2 (P = 1.1 × 10−23), PCDH19 (P = 0.003), SCN1A (P = 9.7 × 10−9), SCN2A (P = 1.9 × 10−4), and SCN8A (P = 3.5 × 10−4)." (PMID 28864458, 2017).
epilepsy (continued). "Structural brain abnormalities appear to be more common in SCN-related epilepsies than previously recognized, particularly in SCN2A and SCN8A, where MRI changes may reflect both developmental disturbances and progressive injury." (PMID 41573391, 2025). "Furthermore, most studies do not provide participant-level clinical details, extended long-term follow-up, or genetic information to support precision therapeutics, with possible exceptions for SCN8A and CDKL5-related epilepsy." (PMID 40944069, 2025). "Despite these gains, currently there are no guidelines for best practices in treating SCN8A-related epilepsy." (PMID 38466077, 2024). "Further studies with larger cohorts, such as polysomnographic studies in SCN8A patients with and without epilepsy of different age groups, are needed to better define the sleep pattern in SCN8A‐related disorders." (PMID 39361253, 2024). "While there is no standard of care treatment for patients with SCN8A-derived epilepsy, from several published studies, sodium channel blockers like oxcarbazepine (OXC) can provide some seizure protection and are well-tolerated." (PMID 38895634, 2024). "We enrolled 47 patients (age range: 2–39 years), whose phenotypes ranged from SCN8A‐DEE to intellectual disability without epilepsy." (PMID 39361253, 2024). "More specific KCNT1 channel blockers may be more effective for treatment of KCNT1, SCN8A, and SCN1A epilepsy." (PMID 37901435, 2023). "We hypothesized that a selective inhibitor of NaV1.6 could provide a safer and more effective treatment for patients with SCN8A-RES and might also be more broadly efficacious in more common forms of epilepsy." (PMID 35234610, 2022). "Despite these promising results, mutation studies of SCN2A in patients with seizure disorders have not shown clearly defined phenotypes unlike SCN1A and SCN8A." (PMID 33841294, 2021). "Thus, unlike some other epilepsy models [e.g., Depdc5, Scn8a, DBA-1, etc.], this model exhibits irregular breathing with only rare and brief apneas during seizures." (PMID 41326205, 2025). "Neuronal sodium channel genes, SCN1A, SCN2A and SCN8A, have been extensively involved in the pathophysiology of a broad spectrum of neurological disorders, including developmental and epileptic encephalopathy (DEE) in which epilepsy and neurodevelopmental comorbidities coexist." (PMID 41515912, 2025). "While a recent study reported that fenfluramine was able to significantly reduce seizure frequency in three patients with SCN8A-derived epilepsy, we did not observe any significant effect on susceptibility to 6 Hz-induced seizures in RL/+ mutants treated with fenfluramine." (PMID 38895634, 2024). "In addition to mutations in the SCN8A gene, non-genetic modifications in Nav1.6 expression and function may also contribute to excitability disorders, such as neuropathic pain, autism-spectrum disorders, ischemia, and stress-induced disorders in addition to epilepsy." (PMID 34202119, 2021). "In addition, targeting Kcnt1 transcript in Scn8a mutant mice doubled their lifespan and extended the survival of Scn1a mutant mice, suggesting KCNT1 could be a therapeutic target for the treatment of SCN1A and SCN8A epilepsy." (PMID 39513870, 2024). "Therefore, phenytoin could be an important treatment option in patients with SCN8A-related epilepsy because it is primarily expected to block the increased sodium current through the mutated Nav1.6, but not to affect the function of other VGSC not affected by the SCN8A mutation." (PMID 26252990, 2016).
Epileptic encephalopathy (55 papers, 2013 to 2026). A condition in which epileptiform abnormalities are believed to contribute to the progressive disturbance in cerebral function. "SCN2A variants, mostly truncations, are associated with autism and intellectual disability, as well as epileptic encephalopathies, while SCN8A variants cause developmental and epileptic encephalopathies with motor symptoms." (PMID 41010287, 2025). "The SCN8A gene is associated with a severe developmental and epileptic encephalopathy, cognitive impairment, and has a demonstrated relationship with reduced pathogenesis of AD in a mouse model study." (PMID 39295643, 2024). "Evaluation of the phenotype and genotype spectrum in SCN8A-related disorders suggests that GoF mutations are associated with severe epileptic encephalopathy, while LoF mutations cause intellectual disability with or without seizures." (PMID 38233770, 2024). "SCN8A variants typically result in a moderate-severe epileptic encephalopathy, and account for 1% of the childhood epileptic encephalopathies." (PMID 38233770, 2024). "Increases in the INaP have been identified as a major factor in many epileptic encephalopathy–causing variants, including both the N1768D and R1872W variants in SCN8A DEE." (PMID 39435659, 2024). "We present a case of a nine-year-old male with SCN8A gene-associated developmental and epileptic encephalopathies (DEEs), characterized by generalized tonic-clonic seizures (GTCS) since infancy." (PMID 38846250, 2024). "Among the new therapeutic strategies, NBI-921352 (formerly known as XEN901), a selective Nav1.6 inhibitor, has been designed to treat early infantile epileptic encephalopathy resulting from GoF SCN8A mutations." (PMID 38003469, 2023). "SCN8A’s role in early neuronal excitability is evidenced by the ability of gain-of-function mutations to cause early infantile epileptic encephalopathy and loss-of-function mutations to cause intellectual disability." (PMID 36997626, 2023). "Heterozygous gain-of-function mutations in SCN8A underlie early infantile epileptic encephalopathy and heterozygous loss-of-function mutations underlie intellectual disability, suggesting an early dose-dependent role of this gene in neuronal function." (PMID 36997626, 2023). "Of note, Scn8a mutations are also present in other disorders with cognitive impairments including epileptic encephalopathies, intellectual disability, and autism spectrum disorders." (PMID 37014118, 2023). "While prior work focused on the role of SCN8A in epileptic encephalopathies, there is evidence in humans and mice that variants in SCN8A are also associated with intellectual disability and neuropsychiatric abnormalities." (PMID 35557557, 2022). "SCN8A‐developmental and epileptic encephalopathy is caused by pathogenic variants in the SCN8A gene encoding the Nav1.6 sodium channel, and is characterized by intractable multivariate seizures and developmental regression." (PMID 35802036, 2022). "In humans, pathogenic SCN8A variants are associated with a wide spectrum of phenotypes, from benign familial infantile seizures to developmental and epileptic encephalopathies." (PMID 35557557, 2022). "Most of the pathogenic SCN8A variants are associated with severe epileptic encephalopathy; however, milder phenotypes associated with missense variants have also been reported." (PMID 34867351, 2021). "The first mouse model of SCN8A epileptic encephalopathy was generated by knock-in of the SCN8A p.N1768D mutation." (PMID 34867351, 2021). "This variant is not observed in the gnomAD database (v3.1.1), and it is adjacent to several reported variants associated with epileptic encephalopathy, including p.L1865P, E1870D, and R1872 which is one of the most frequently mutated SCN8A residues." (PMID 34867351, 2021). "SCN2A and SCN8A mutations have been reported in some patients with severe epileptic encephalopathies." (PMID 33841294, 2021).